NRXN1 (neurexin 1)
Description:
Cell surface protein involved in cell-cell-interactions, exocytosis of secretory granules and regulation of signal transmission. Function is isoform-specific. Alpha-type isoforms have a long N-terminus with six laminin G-like domains and play an important role in synaptic signal transmission. Alpha-type isoforms play a role in the regulation of calcium channel activity and Ca(2+)-triggered neurotransmitter release at synapses and at neuromuscular junctions. They play an important role in Ca(2+)-triggered exocytosis of secretory granules in pituitary gland. They may affect their functions at synapses and in endocrine cells via their interactions with proteins from the exocytotic machinery. Likewise, alpha-type isoforms play a role in regulating the activity of postsynaptic NMDA receptors, a subtype of glutamate-gated ion channels. Both alpha-type and beta-type isoforms may play a role in the formation or maintenance of synaptic junctions via their interactions (via the extracellular domains) with neuroligin family members, CBLN1 or CBLN2. In vitro, triggers the de novo formation of presynaptic structures. May be involved in specification of excitatory synapses. Alpha-type isoforms were first identified as receptors for alpha-latrotoxin from spider venom. Neuronal cell surface protein involved in cell recognition and cell adhesion by forming intracellular junctions through binding to neuroligins (By similarity). Plays a role in formation of synaptic junctions (By similarity). Functions as part of a trans-synaptic complex by binding to cerebellins and postsynaptic GRID1. This interaction helps regulate the activity of NMDA and AMPA receptors at hippocampal synapses without affecting synapse formation. NRXN1B-CBLN2-GRID1 complex transduce presynaptic signals into postsynaptic NMDAR response (By similarity).
Synonyms: KIAA0578; Hs.22998; PTHSL2; SCZD17
Tractability: Antibody: its Gene Ontology location is reachable by antibodies, with high confidence; UniProt places it where antibodies can reach, with medium confidence; UniProt predicts a signal peptide or a membrane-spanning region; the Human Protein Atlas places it where antibodies can reach. PROTAC: its protein half-life has been measured.
Gene: Protein-coding gene on chromosome 2 (49,918,503 to 51,225,575, reverse strand). Ensembl gene ENSG00000179915.
Subcellular location: Presynaptic cell membrane
Subcellular location (Human Protein Atlas): Plasma membrane; Nucleoli; Nucleoplasm
Pathways (Reactome):
Extracellular matrix organization: Non-integrin membrane-ECM interactions
Neuronal System: Neurexins and neuroligins
Gene Ontology:
Molecular function: protein binding; acetylcholine receptor binding; calcium channel regulator activity; calcium ion binding; cell adhesion molecule binding; neuroligin family protein binding; signaling receptor activity; transmembrane signaling receptor activity
Biological process: adult behavior; learning; neuromuscular process controlling balance; social behavior; vocal learning; vocalization behavior; axon guidance; chemical synaptic transmission; gephyrin clustering involved in postsynaptic density assembly; nervous system development; neuroligin clustering involved in postsynaptic membrane assembly; neuron cell-cell adhesion; neurotransmitter secretion; positive regulation of excitatory postsynaptic potential; positive regulation of synapse assembly; positive regulation of synapse maturation; positive regulation of synaptic transmission, glutamatergic; postsynaptic density protein 95 clustering; postsynaptic membrane assembly; signal transduction; synapse assembly
Cellular component: cell surface; endoplasmic reticulum; neuronal cell body; nuclear membrane; plasma membrane; presynaptic active zone membrane; presynaptic membrane; trans-synaptic protein complex; vesicle
Genetic constraint (gnomAD): Loss-of-function variants: 29 observed, 124.82 expected, observed/expected ratio (o/e) 0.23, 90% interval 0.17 to 0.32. The synonymous counts are far from expectation, so gnomAD's model fits this gene poorly and the ratio says little. Missense variants: 1,749 observed, 1,903.8 expected, observed/expected ratio (o/e) 0.92, 90% interval 0.88 to 0.96. Synonymous variants: 896 observed, 739.45 expected, observed/expected ratio (o/e) 1.21, 90% interval 1.15 to 1.28.
Gene-disease validity (ClinGen):
ClinGen rates the evidence that NRXN1 causes each of these diseases.
complex neurodevelopmental disorder (autosomal dominant): Definitive. A disorder that involves more than one phenotype associated with the central nervous system, including but not limited to intellectual disability, autism, and seizures (epilepsy).
Homologues: Orthologues: chimpanzee NRXN1 (99% identical), macaque NRXN1 (99% identical), rabbit NRXN1 (99% identical), mouse Nrxn1 (99% identical), dog NRXN1 (99% identical), rat Nrxn1 (97% identical), tropical clawed frog nrxn1 (89% identical), pig NRXN1 (74% identical), zebrafish nrxn1b (69% identical). Paralogues in human: NRXN2 (69% identical), NRXN3 (69% identical), CNTNAP5 (21% identical), CNTNAP4 (20% identical), CNTNAP2 (19% identical), CNTNAP3 (19% identical), CNTNAP3B (19% identical), CNTNAP1 (18% identical), CUBN (11% identical), F5 (10% identical), F8 (10% identical), HEPH (10% identical), and 23 more.
Diseases named in the same sentence as NRXN1 in open-access papers:
NRXN1 is named in the same sentence as 124 diseases in open-access papers, as found by Europe PMC text mining. Sharing a sentence is not in itself a finding about the gene and the disease. The quoted sentences say what the papers report.
schizophrenia (127 papers, 2008 to 2026). A major psychotic disorder characterized by abnormalities in the perception or expression of reality. "Animal studies demonstrate that LRRTM2 plays an important role in hippocampal connectivity, and genetic studies show that NRXN1 is involved in a variety of neuropsychiatric traits, including schizophrenia, nicotine dependence and risk of suicide." (PMID 41044382, 2026). "Exonic deletions in NRXN1, particularly those affecting the NRXN1α isoform, have been found to confer substantially elevated risk for schizophrenia, with odds ratios (OR) ranging from 7.44 to 14.4 in large multi-cohort studies." (PMID 41333154, 2025). "Mutations in NRXN1 are associated with schizophrenia, autism spectrum disorder, and other neurodevelopmental abnormalities." (PMID 40128298, 2025). "For example, copy number variation in NRXN1, which encodes a synaptic scaffolding protein, has a penetrance of 6.4% for schizophrenia and 26% for ASD or ID." (PMID 39849619, 2025). "Several studies have identified recurrent structural genetic variations within the NRXN1 locus in schizophrenia patients, including intronic deletions and other mutations." (PMID 39966624, 2025). "When examining RCV enrichment in genes impacted by schizophrenia risk CNVs, an excess of PTVs in NRXN1 was observed in cases compared with controls." (PMID 40753099, 2025). "Nrxn1 mutations cause a variety of neurological diseases, including attention deficit hyperactivity disorder, intellectual disability, seizures, schizophrenia, and mood disorders, suggesting its important role in the nervous system." (PMID 39456437, 2024). "Previous studies have revealed that NRXN1 is associated with neurological diseases and developmental disorders, such as schizophrenia." (PMID 38310240, 2024). "Human genetic studies have linked disruptions in all three human Nrxn genes (NRXN1-3) to neurodevelopmental disorders such as autism spectrum disorders (ASDs) and schizophrenia (SCZ)." (PMID 38279285, 2024). "Multiple lines of evidence implicate deletions in gene NRXN1 with BF of 46.31, implying that it is related to conferring a risk of schizophrenia." (PMID 39202013, 2024). "Copy number deletions in 2p16.3 locus (NRXN1) in individuals significantly increase risk for schizophrenia." (PMID 37355690, 2023). "The engineering of heterozygous schizophrenia-associated NRXN1 mutations induced electrophysiological impairment in neurons generated through the expression of neurogenin-2." (PMID 37441676, 2023). "De novo mutations and copy number deletions in NRXN1 (2p16.3) pose a significant risk for schizophrenia (SCZ)." (PMID 37355690, 2023). "Neurexin genes have been associated with changes in human behavior, where variants in NRXN1 are associated with autism, schizophrenia, and Tourette syndrome." (PMID 38036526, 2023). "Deletion and missense mutations in all three Neurexin genes have been identified in psychiatric disorders, with mutations in the NRXN1 gene most strongly linked to schizophrenia (SZ) and autism spectrum disorder (ASD)." (PMID 36307390, 2022). "Recent genetics research has linked NRXN1 missense mutations to increased risk for brain disorders, including schizophrenia (SCZ) and autism spectrum disorder (ASD)." (PMID 35627176, 2022). "For example, NRXN1, which is most highly expressed in late gestation and early childhood and is a target of schizophrenia-associated CNVs, appears to serve a role in synapse formation." (PMID 34974922, 2022). "Previous studies showed that several missense and structural variations in NRXN1 are associated with autism, schizophrenia, developmental abnormalities, and psychiatric drug response." (PMID 34168285, 2021). "The most common phenotype associated with NRXN1 deletions in clinical samples is ID, although schizophrenia, ASD and TS are also associated." (PMID 33752146, 2021). "One of the first findings was a correlation of deletions in NRXN1 (Neurexin 1) gene and schizophrenia risk." (PMID 35053755, 2021).
schizophrenia (continued). "2p16.3 deletions, involving heterozygous NEUREXIN1 (NRXN1) deletion, dramatically increase the risk of developing neurodevelopmental disorders, including autism and schizophrenia." (PMID 31812984, 2020). "The association between the polymorphisms of the TCF4 gene and NRXN1 gene with schizophrenia has been reported in many studies (19, 20, 21, 22, 23, and 24)." (PMID 32071599, 2019). "Intriguingly, several schizophrenia-associated genes such as NRXN1 and LAMA2 also contain LamG domains." (PMID 29302076, 2019). "Genetic studies have shown that neurexin 1 gene can be considered as a candidate gene for the development of the human brain to cause mental disorders, such as schizophrenia, autism, and mental retardation." (PMID 32071599, 2019). "Structural copy number variants (CNVs) disrupting NRXN1 are associated with a wide spectrum of brain disorders including schizophrenia, autism, and developmental disorders." (PMID 31530798, 2019). "This case-control study aimed to investigate the correlation of TCF4 rs13381800 and NRXN1 rs17039988 polymorphisms with the risk of schizophrenia in a sample of Iranian patients with schizophrenia." (PMID 32071599, 2019). "Identification of candidate single-nucleotide polymorphisms in NRXN1 related to antipsychotic treatment response in patients with schizophrenia." (PMID 30093869, 2018). "We found that DISC1 interacts with Neurexin (NRXN1), which encodes a family of synaptic adhesion molecules implicated as a risk factor of various psychiatric disorders including schizophrenia and autism spectrum disorders." (PMID 29079805, 2017). "For example, the schizophrenia-associated CNV deletion at 2p16.3 has been shown to disrupt NRXN1 gene, a member of the neurexin family, because the promoter and first exon of the NRXN1 gene fall within the interval of the CNV." (PMID 28680393, 2017). "CNVs that affect the neurexin 1 gene (NRXN1) increase the risk of an individual developing schizophrenia, and neurexin 1 is critical to the formation and function of synapses." (PMID 28253899, 2017). "This is also similar to another gene, NRXN1, the deletion of which is significantly associated with schizophrenia." (PMID 29191242, 2017). "NRXN1 (neurexin 1) has been implicated in schizophrenia and plays an important role in the nervous system by mediating, among others, cell-cell interactions and signal transmission." (PMID 27319317, 2016). "This is particularly interesting for the Nrxn gene family as Nrxn1 mutations are associated with autism and schizophrenia in the human population." (PMID 25985086, 2015). "Rare exonic variants in the well-established ASD and schizophrenia candidate gene NRXN1 show nominal association (p = 0.041)." (PMID 26185613, 2015). "For example, rare NRXN1 deletions are associated with schizophrenia and show variable breakpoints and lengths among schizophrenia cases." (PMID 26431523, 2015). "Deletions in the 2p16.3 region that includes the neurexin (NRXN1) gene are associated with intellectual disability and various psychiatric disorders, in particular, autism and schizophrenia." (PMID 25614873, 2014). "A later study of 2977 schizophrenia patients and 33746 controls examined Nrx1 for copy number variants (CNVs) and identified 66 deletions and 5 duplications in NRXN1 from the patients, confirming that Nrx1 is a risk gene for schizophrenia." (PMID 24756565, 2014). "These usually change copy number of multiple genes, but deletions at 2p16.3, which have been associated with autism, schizophrenia and mental retardation, affect only the neurexin 1 gene, usually the alpha isoform." (PMID 23840597, 2013). "Among them, NRXN1, especially exonic deletions in the α-NRXN1 isoform, represents one of the most robust associations for autism, schizophrenia and other developmental disorders." (PMID 23536886, 2013).
schizophrenia (continued). "NRXN1 encodes a neuronal cell surface protein involved in cell recognition and cell adhesion and genome-wide CNV studies have previously implicated NRXN1 deletions in autism and schizophrenia and in AD." (PMID 24073418, 2013). "Microdeletions in the NRXN1 gene have been associated with a range of neurodevelopmental disorders, including autism spectrum disorders, schizophrenia, intellectual disability, speech and language delay, epilepsy and hypotonia." (PMID 25408897, 2013). "Exonic deletions in NRXN1 have been associated with several neurodevelopmental disorders, including autism, schizophrenia and developmental delay." (PMID 23536886, 2013). "Numerous studies have reported associations between hemizygous exonic deletions within the NRXN1 gene (2p16.3) and neurodevelopmental disorders, including intellectual disability, developmental delay, autism and schizophrenia." (PMID 23840597, 2013). "Neurexin-1 has also been associated with autism spectrum disorder and schizophrenia in humans, and self-grooming behavior in mice." (PMID 23133594, 2012). "The NRXN1 gene has been associated with autism, schizophrenia, and has been shown to have reduced expression with increasing AD severity." (PMID 23227193, 2012). "The relationship between the genetic variants in the middle or 3'-end region of NRXN1 gene and schizophrenia would be verified in the future study." (PMID 21477380, 2011). "In the present study, we investigated the association of NRXN1 polymorphisms and schizophrenia in 768 cases and 738 healthy control subjects of Chinese Han population." (PMID 21477380, 2011). "The biological effect of risk variants and haplotypes in the NRXN1 gene associated with schizophrenia, and their role in disease pathogenesis and clinical characteristics, needs to be explored." (PMID 21477380, 2011). "Other chromosomal mutations have also been found in schizophrenia such as deletions of 3q29 and NRXN1 and duplications of 15q11-q13 (maternal), 16p11.2, and 16p13.3." (PMID 22118685, 2011). "The gene variants that influenced brain morphology in our study are located in the regions of NRXN1 susceptible to deletion in schizophrenia and ASD." (PMID 21687627, 2011). "We found that genetic variation in the 3′untranslated region of the NRXN1 gene predicted an intermediate risk phenotype in healthy individuals relevant to schizophrenia and ASD." (PMID 21687627, 2011). "The association of NRXN1 polymorphisms with schizophrenia and the age-at-onset of this disease were explored." (PMID 21477380, 2011). "In the present study, we did not do any association analyses of child-onset schizophreia with NRXN1 polymorphisms, since we have only five patients with age-at-onset less than 12 years old in our 768 patients with schizophrenia." (PMID 21477380, 2011). "For instance, recurrent CNVs involving the putative schizophrenia risk genes NRXN1 and erbB4 are reported in control populations." (PMID 22547958, 2011). "Chromosomal deletions of 1q21.1, 3q29, 15q13.3, 22q11.2, and NRXN1 and duplications of 15q11-q13 (maternal), 16p11, and 16p13.3 have the strongest association with schizophrenia." (PMID 22118685, 2011). "In conjunction with our in silico results, our findings provide evidence for a neural and cognitive susceptibility mechanism by which the NRXN1 gene confers risk for both schizophrenia and ASD." (PMID 21687627, 2011). "Our results showed that four SNPs of NRXN1 gene were significantly associated with schizophrenia (rs10490168: G > A, p = 0.017; rs2024513: A > G, p = 0.006; rs13382584: T > C, p = 0.009; and rs1558852: G > A, p = 0.031)." (PMID 21477380, 2011). "In this study, we attempted to investigate the association between the NRXN1 gene polymorphisms and schizophrenia and age-at-onset of this disease in 768 patients with schizophrenia and 738 healthy control subjects of Chinese Han population." (PMID 21477380, 2011).